MAP3K20-AS1 (MAP3K20 antisense RNA 1)
Synonyms: MLK7-AS1
Gene: Long non-coding RNA gene on chromosome 2 (173,166,446 to 173,282,036, reverse strand). Ensembl gene ENSG00000238133.
Diseases named in the same sentence as MAP3K20-AS1 in open-access papers:
MAP3K20-AS1 is named in the same sentence as 1 disease in open-access papers, as found by Europe PMC text mining. Sharing a sentence is not in itself a finding about the gene and the disease. The quoted sentences say what the papers report.
cancer (1 paper, 2022). A tumor composed of atypical neoplastic, often pleomorphic cells that invade other tissues. "MAP3K20 antisense RNA 1 (MAP3K20-AS1) also known as MLK7-AS1, has been mostly studied in cancer, and its reduced expression plays a role in promoting the proliferation of cancer cells." (PMID 35235759, 2022).